SMARCA4 (SWI/SNF related BAF chromatin remodeling complex subunit ATPase 4)
Diseases named in the same sentence as SMARCA4 in open-access papers (continued):
Sharing a sentence is not in itself a finding about the gene and the disease.
malignant rhabdoid tumors (continued). "Accumulation of the chromatin remodeling protein SMARCA4 (BRG1) leads to the loss of PRCs at Pou5f1 in mouse cells and at INK4b-ARF-INK4a in human malignant rhabdoid tumor cells." (PMID 31947658, 2020). "Whereas mutations in the SMARCA4 gene and the related SMARCB1 gene also occur in malignant rhabdoid tumors, further similarities by whole exome sequencing suggested SCCOHT as malignant rhabdoid tumor of the ovary." (PMID 26436697, 2015). "None of these individuals had a history of rhabdoid tumors; however, a regular oncological follow-up was established following the SMARCA4 variant identification." (PMID 41568967, 2026). "While these tumors differ in their methylation pattern from their SMARCB1 deleted counterparts, heterozygous aberrations in SMARCA4 so far have not been implicated in the biology of rhabdoid tumors." (PMID 41168858, 2025). "Due to the high degree of dedifferentiation observed in SMARCA4-deficient undifferentiated RCC, these tumors are morphologically similar to SMARCB1-deficient malignant rhabdoid tumor (MRT), rhabdomyoblastic RCC, and other small round cell undifferentiated tumors, which can lead to misdiagnosis." (PMID 41312169, 2025). "Furthermore, these tumors exhibit shared transcriptomic and phenotypic features with aggressive SMARCA4-deficient malignancies occurring at other sites, including SSCOHT and malignant rhabdoid tumor." (PMID 38180245, 2024). "Also, a de novo GPV in SMARCA4 has been observed in a patient with early-onset OC and other types of childhood/early-onset rhabdoid tumors." (PMID 38069345, 2023). "None harbored mutation or deletion of the SMARCB1 or SMARCA4 genes, thereby distinguishing these tumors from atypical teratoid/rhabdoid tumors." (PMID 36437415, 2023). "TILs therapy may represent a novel approach for rhabdoid tumors, as TILs could recognize specific aberrations in SWI/SNFc, such as complete loss of SMARCA4 or SMARCB1 or other neoantigens created by epigenetic changes occurring within the tumor." (PMID 37446319, 2023). "Furthermore, GPVs in SMARCA4 were associated with small cell carcinoma of the ovary hypercalcemic type (SCCOHT), a rare, aggressive OC similar to malignant rhabdoid tumors that primarily affects women under 40 years of age." (PMID 38069345, 2023). "Based on the mechanism of the preclinical efficiency of CDK4/6 inhibitor acting on SMARCA4-defective tumors, a phase I study of the CDK4/6 inhibitor Ribociclib (LEE011) was conducted in pediatric patients with rhabdoid tumors harboring SWI/SNF subunits with a high mutation rate." (PMID 36361605, 2022). "The diagnosis of RTPS is established in a proband with a rhabdoid tumor and/or a family history of RT and/or multiple SMARCB1/SMARCA4 deficient tumors (synchronous or metachronous) and identification of a germline pathogenic variant in SMARCB1 or SMARCA4 by genetic testing." (PMID 33692948, 2021). "Transcriptome analyses aligned SMARCA4‐UTs more closely with SMARCA4‐mutated SCCOHTs and SMARCB1‐inactivated malignant rhabdoid tumors (MRTs) rather than conventional NSCLCs." (PMID 38124509, 2023). "Malignant rhabdoid tumors are associated with germline mutations of SMARCB1 or SMARCA4, whereas no SMARCA4 germline mutations have been reported in SMARCA4-deficient thoracic sarcomas." (PMID 34131151, 2021). "Tazemetostat is a potent and highly selective EZH2 inhibitor that has shown antitumor activity in vitro and in SMARCA4-negative malignant rhabdoid tumor of the ovary." (PMID 31996670, 2020).
colorectal cancer (55 papers, 2010 to 2026). A primary or metastatic malignant neoplasm that affects the colon or rectum. "SMARCA4 is a novel key epigenetic modulator of colorectal cancer, and SMARCA4 may directly influence the loss of DNA methylation, which provided insight of aberrant gene induction during tumor progression." (PMID 34675941, 2021). "However, the mechanisms of tumorigenesis driven by SMARCA4 mutations, particularly in colorectal cancer (CRC), remain largely unknown." (PMID 36922568, 2023). "PRMT1-mediated H4R3me2a recruits SMARCA4, which promotes colorectal cancer progression by enhancing EGFR signaling." (PMID 33853662, 2021). "Nonetheless, we provide evidence to show that SMARCA4 promotes colorectal cancer cell proliferation by interacting with PRMT1 to activate TNS4 and EGFR transcription." (PMID 33853662, 2021). "In colorectal cancer, inhibition of SMARCA4 led to activation of the JNK pathway." (PMID 39697230, 2024). "This confirms previous literature that SMARCA4 uniquely acts as a tumor promoter in colorectal cancer, and may present a new role of SMARCA4 in tumorigenesis in CRC with a KRAS mutation." (PMID 38446332, 2024). "It has been reported that SMARCA4 synergizes with RUNX2 to promote EMT in colorectal cancer cells." (PMID 36902184, 2023). "In colorectal cancer, PRMT1 cooperates with chromatin subfamily A member 4 (SMARCA4) to activate EGFR signaling, promoting malignant transitions." (PMID 40612681, 2025). "The nuclease benzonase was included in all buffers to minimize post-lysis DNA binding by cGAS, then Co-IP validated interactions between cGAS and SWI/SNF components such as ARID1A, SMARCA4 and SMARCC2 in colorectal cancer cells." (PMID 39080411, 2024). "We show that PRMT1 and SMARCA4, an ATPase subunit of the SWI/SNF chromatin remodeling complex, act cooperatively to promote colorectal cancer (CRC) progression." (PMID 33853662, 2021). "Additionally, SMARCA4 recruited by PRMT1-mediated H4R3me2a enhances EGFR signaling and TNS4 expression in colorectal cancer, with elevated PRMT1 or SMARCA4 levels positively correlating with increased EGFR and TNS4 expression and decreased overall survival." (PMID 40906372, 2025). "To determine the effects of SP-2577 on SWI/SNF-mutant cell viability, we performed drug-dose-response (DDR) studies with 72 h CellTiterGlo viability endpoints in SCCOHT (SMARCA4-/-), OCCC (ARID1A-/-), lung (SMARCA4-/-), kidney (SMARCB1-/-), and colorectal cancer cell lines (SMARCA4-/-)." (PMID 32649682, 2020). "In addition, we also found that miR-6511b-5p can directly target brahma-related gene 1 (BRG1), also known as SMARCA4, a key regulator of CD44 and a major transcriptional regulator, to suppress invasion and migration by regulating CD44 in pMMR colorectal cancer cells." (PMID 35590122, 2022).
melanoma (55 papers, 2009 to 2026). A malignant, usually aggressive tumor composed of atypical, neoplastic melanocytes. "SMARCA2 mutations occur at almost the same frequency as SMARCA4 mutations in patient derived melanomas." (PMID 35323214, 2022). "Exome studies of patient-derived melanomas have revealed mutations in SMARCA4, some of which are predicted to cause loss of function." (PMID 35323214, 2022). "Depletion of SMARCA2 in SMARCA4-deficient melanoma cells abrogates melanoma tumorigenicity and systematic studies in other cancers have shown that loss of one subunit renders cells highly dependent on the paralogous subunit." (PMID 35323214, 2022). "BRAF variants (P336L, G73E and V207E) and SMARCA4 variants (P262L, P919S, E1113K, H884Y) were detected in 3 melanoma BM." (PMID 33578810, 2021). "SMARCA4 mRNA was seen to be down-regulated in bladder, colon, non-triple negative breast cancers, head and neck, oesophageal, melanoma, pancreatic, lung and ovarian cancers, and SMARCA4 mutation rates in these cancers have been reported between 4 and 13%." (PMID 33596994, 2021). "Inactivating mutations in this complex (ARID2A, ARID1A and SMARCA4) are found in 13% of melanomas, highlighting their role as tumor suppressors and emphasizing the importance of this complex in normal biology and disease." (PMID 26426052, 2015). "Also, SMARCA4 mutation and reduced SMARCA4 copy number predicted favourable prognosis in melanoma patients." (PMID 36317703, 2022). "In addition to mutations, there have been variable reports of SMARCA4 protein expression in patient-derived melanoma tumors." (PMID 35323214, 2022). "Despite this hypothesis, SMARCA2 was shown to interact with MITF and to partially compensate for SMARCA4 loss in the regulation of MITF-target genes in melanoma cells." (PMID 35323214, 2022). "Thus, SMARCA4 status may be heterogeneous in melanoma, with some tumors exhibiting SMARCA4 loss of function while in other contexts, high levels of SMARCA4 may promote tumorigenesis." (PMID 35323214, 2022). "In our analysis, alterations in genes regulating the SWI/SNF chromatin remodeling complex (LoF ARID2, LoF ARID1A, and SMARCA4) were most frequent in Class 3 melanomas." (PMID 38275886, 2024). "The differential diagnosis includes gastric carcinoma with SMARCA4 deficiency, undifferentiated carcinomas, EBV-associated carcinoma, lymphoma, melanoma, germ cell neoplasms, and so on." (PMID 38090508, 2023). "In light of accumulated data, ARID2, ARID1B, SMARCA4 (BRG1), and SMARCA2 (BRM) have the most important mutations in melanoma." (PMID 36844227, 2023). "SMARCA4 and its paralogue SMARCA2 are almost equally frequently mutated (mostly as missenses) in patients with melanoma." (PMID 36844227, 2023). "In melanoma, SMARCA4 binds and is required for active enhancer function near melanocyte development genes." (PMID 35323214, 2022). "The expression of SMARCA4 was elevated with the proliferation potential of melanoma and effectively predicted the prognosis of metastatic and proliferative melanoma patients." (PMID 36317703, 2022). "A genome-wide study in melanoma cells confirmed that SMARCA4 cooperates with MITF to remodel chromatin at pigmentation loci and other MITF-target genes." (PMID 35323214, 2022). "It will be important to identify the contexts in which high or low SMARCA4 levels are advantageous to melanoma cells." (PMID 35323214, 2022). "Meanwhile, SMARCA4 was reported to regulate SOX10 expression or function as a co‐activator of SOX10 in melanoma." (PMID 36317703, 2022). "Consistently, somatic mutations and decreased copy number of SMARCA4 predicted a tendency towards the favourable outcome of melanoma patients, indicating SMARCA4 was involved in the proliferation of melanoma." (PMID 36317703, 2022). "To better elucidate the biological function of SMARCA4 in melanoma, we examined the proliferation ability and the clonogenic ability of M14 and A375 cells." (PMID 36317703, 2022).
melanoma (continued). "With multivariate Cox regression, SMARCA4 (also known as BRG1) was identified as an independent prognostic marker for melanoma patients." (PMID 36317703, 2022). "By looking into the expression pattern of marker genes in Cluster 3 patients, we set up a multivariate Cox regression model and selected SMARCA4 as the potential prognostic marker for melanoma." (PMID 36317703, 2022). "MITF-independent mechanisms by which SMARCA4 promotes melanoma survival and invasiveness have also been reported." (PMID 35323214, 2022). "To further explore the function of SMARCA4, we compared the proliferation and clonogenic ability of SMARCA4‐depleted melanoma cells." (PMID 36317703, 2022). "Other studies showed that SMARCA4 is critically required for an extensive number of MITF as well as MITF-targets that are pro-survival genes in melanoma and for melanoma survival in vitro." (PMID 35323214, 2022). "High proliferation (> 40%) was observed in melanoma, epithelioid sarcoma (ES), malignant SFT, and SMARCB1- and SMARCA4-deficient neoplasms." (PMID 34350470, 2021). "FBOX32 by interacting with chromatin remodeling complexes containing SMARCA4 regulates the transcriptional repertoire and multiple key biological functions, responsible of melanoma progression and dissemination." (PMID 33462405, 2021). "Especially, loss-of-function mutation in components of this complex such as ARID2, ARID1A, ARID1B or SMARCA4 are found in 13% of melanomas, suggesting a tumor suppressor role and highlighting the importance of chromatin remodeling in melanomagenesis 72,73." (PMID 32042336, 2020). "Furthermore, in a study of melanoma cells exposed to UV light, SMARCA4 and MITF inhibited apoptosis and enhanced the trans-responsive effects of the melanoma apoptosis inhibitor ML-IAP." (PMID 39697230, 2024). "However, it must be noted that many poorly differentiated neoplasms have also been shown to exhibit distinct neuroendocrine differentiation, such as SMARCA4- or SMARCB1-deficient cancers, NUT cancers, melanoma and others." (PMID 39049067, 2024). "Loss-of-function mutations in the components of the SWI/SNF complex such as AT-rich interactive domain-containing protein 1A (ARID1A), ARID1B, ARID2, or SMARCA4 are common in melanoma, suggesting that altered chromatin remodeling plays a role in the pathogenesis of this disease." (PMID 36844227, 2023). "Thus, the relationship between SMARCA4 and ARID2 would be a potential target for synthetic lethal therapy, as SMARCA4 and ARID2 are frequently mutated in melanoma." (PMID 36844227, 2023). "Here, we hypothesized that SOX10 could transcriptionally modulate SMARCA4 expression and maintain melanoma cell proliferation." (PMID 36317703, 2022). "Furthermore, inactivation of Smarca4 delays tumor formation in a mouse melanoma model driven by oncogenic BRAF/inactivated PTEN." (PMID 35323214, 2022). "However, the crucial role of SMARCA4 in the elimination of replication stress in melanoma remains elusive." (PMID 36317703, 2022). "Mechanistically, we demonstrated that SMARCA4 could resolve DNA replication stress and guarantee the proliferation of melanoma cells." (PMID 36317703, 2022). "While it seems a long way to find a promising approach for melanoma, we believe SMARCA4 could be a promising target for the treatment of melanoma patients." (PMID 36317703, 2022). "Besides, SMARCA4 was a promising prognostic marker for the disease‐free interval (DFI) in melanoma patients and was significantly elevated in melanoma patients, compared with normal skin tissues." (PMID 36317703, 2022). "The result showed reduced proliferation and clonogenic ability in SMARCA4‐depleted melanoma cells." (PMID 36317703, 2022). "SMARCA4 increases resistance to DNA-damaging agents in melanoma." (PMID 35323214, 2022). "To decipher potent prognostic markers for melanoma, we performed the Kaplan–Meier analysis and observed only SMARCA4 could accurately predict the unfavourable prognosis of melanoma patients." (PMID 36317703, 2022).
melanoma (continued). "Thus, disruption of SMARCA4 function is likely to contribute to the initiation of melanoma through multiple mechanisms." (PMID 35323214, 2022). "Thus, there is evidence that SMARCA4 is disrupted in melanoma, such as it is in several other cancers." (PMID 35323214, 2022). "Furthermore, we predicted the binding of different transcription factors on the SMARCA4 promoter and unveiled the modulated expression of SMARCA4 by SOX10 in melanoma." (PMID 36317703, 2022). "Therefore, we were devoted to unveiling the prognostic value and the biological function of SMARCA4 in melanoma." (PMID 36317703, 2022). "Loss-of-function mutations in the SWI/SNF complex components such as AT-rich interactive domain-containing protein 1A (ARID1A), ARID1B, ARID2, or SMARCA4 are frequent in melanoma, suggesting that altered chromatin remodeling plays a role in the pathogenesis of this disease." (PMID 34440824, 2021). "Among our chromograninA, negative MN-NEs were SFT, ES, SMARCA4-deficient neoplasm, melanoma, and chordoma." (PMID 34350470, 2021). "Moreover, the SP‐01 tumor presents an activating mutation in the ERBB4 gene, which is described as a driver of BRAF wild‐type (WT) melanomas, and SP‐06 presents an oncogenic NRAS mutation, inactivation of NF2, and a truncating mutation in SMARCA4 (in one allele)." (PMID 37798904, 2024). "Thus, the repertoire of transcription factors present in melanoma may dictate whether SMARCA4 has tumor-suppressive or oncogenic roles by regulating SMARCA4 genomic localization." (PMID 35323214, 2022). "However, some studies have shown that SMARCA4 may also promote melanoma proliferation, invasiveness, and response to therapeutics." (PMID 35323214, 2022). "SMARCA4 regulates MITF, melanin synthesis, protection against UVR damage, and survival in melanocytes and melanoma cells." (PMID 36844227, 2023). "Pearson regression results from 4 different melanoma databases showed that SOX10 and USF2 were positively correlated with the expression of SMARCA4, yet TBX15 and ETS2 were negatively correlated with the expression of SMARCA4." (PMID 36317703, 2022). "Both SOX10 and TBX15 were correlated with the unfavourable prognosis of melanoma patients, and SOX10 positively correlates with SMARCA4." (PMID 36317703, 2022). "Together, we performed integrated approaches to identify SMARCA4 as a promising prognostic marker for melanoma, which was transcriptionally regulated by SOX10 and promoted melanoma cell proliferation by ameliorating DNA replication stress." (PMID 36317703, 2022). "It will be important to further evaluate potential synthetic lethality between SMARCA4 and SMARCA2 in melanoma." (PMID 35323214, 2022). "SMARCA4 was found to regulate MITF expression and to interact with MITF in melanoma cells, thereby promoting expression of an extensive number of pigmentation genes." (PMID 35323214, 2022). "Although SMARCA4 and SMARCB1 are also required for SWI/SNF-mediated chromatin remodeling at lineage-specific enhancers, loss of these subunits may be inconsistent with melanocyte and melanoma viability under most contexts due to their broader role in the regulation of gene expression." (PMID 35323214, 2022). "FBXO32 and SMARCA4 are the components of a molecular cascade, linking MITF to epigenetics, in melanoma cells." (PMID 33462405, 2021). "Although not as frequently mutated in melanoma as ARID2 and SMARCA4, PBRM1 protein levels are highly sensitive to the levels of SMARCA4 protein and incorporation into the SWI/SNF complex requires the presence of ARID2." (PMID 35323214, 2022). "The result showed that SMARCA4, XAB2 and NUDT1 were potent markers for the overall survival (OS) and disease‐specific survival (DSS) and SMARCA4 was shown to correlate with XAB2 and NUDT1 expression in melanoma patients." (PMID 36317703, 2022).
melanoma (continued). "Further analysis revealed that SMARCA4 especially correlated with favourable prognosis in metastatic and highly proliferative melanoma patients, but not in primary melanoma patients." (PMID 36317703, 2022). "The expression of SMARCA4 is not altered after dabrafenib or vemurafenib treatment in melanoma patients and is highly increased in proliferative melanoma and ki67 positive (>30%) melanoma." (PMID 36317703, 2022). "SMARCA4 gene was highly methylated in the TCGA database and cg08151828, cg26967868 and cg23963476 showed the highest correlation with SMARCA4 mRNA level, among which cg23963476 is negatively correlated with SMARCA4 and correlates with the survival of melanoma patients." (PMID 36317703, 2022). "The pathological function of multiple DNA damage repair‐related genes, especially the NER‐related genes, in the carcinogenesis and the progression of melanoma has been suggested, yet how SMARCA4 promotes the proliferation of melanoma cells has not been discussed." (PMID 36317703, 2022). "Interestingly, we identified variants in five new candidate genes, i.e., ARID1A, ARID2, SMARCA4, PIK3R1 and BAP1, which neither have been previously identified in melanoma BM nor reported in CNS metastases from other cancers." (PMID 33578810, 2021). "Moreover, we detected single nucleotide transitions in ARID1A, ARID2, SMARCA4 and BAP1, all genes which have not been associated before with CNS metastases of melanomas." (PMID 33578810, 2021).